CD40 (CD40 molecule)
Diseases named in the same sentence as CD40 in open-access papers (continued):
Sharing a sentence is not in itself a finding about the gene and the disease.
glioblastoma (25 papers, 2014 to 2026). The most malignant astrocytic tumor (WHO grade IV). "Similar associations were observed in the CGGA-glioblastoma cohort for CD40, CD276, TNFRSF14, and TNFSF14, except for TNFSF4 and TNFRSF18." (PMID 38365809, 2024). "Recently we have shown that CD40 on the surface of C6 glioblastoma cells is a target for Hsp70 linked to magnetic nano-particles." (PMID 24797019, 2014). "Therefore, the aims of this study were to characterize the role of LAPTM5 in glioblastoma, to elucidate its interaction with CD40, and to analyze the underlying signaling pathways involved in tumorigenicity." (PMID 32582531, 2020). "Furthermore, we demonstrated that high LAPTM5 expression is associated with improved overall survival in CD40 high-expressing glioblastoma." (PMID 32582531, 2020). "In various immunologically “cold” tumor models, including pancreatic adenocarcinoma and glioblastoma, agonistic CD40 antibodies (aCD40) have successfully activated cDC1s, improved T cell priming, and enhanced anti-tumor immunity." (PMID 40585246, 2025). "Knowing the fact that in glioblastoma, upregulation of the CD40/CD40L axis is an indicator for better prognosis, it is interesting that in vivo, the use of this anti-CD40 agonist antibody actually shows anti-tumor effects." (PMID 35214076, 2022). "In contrast, a recent study identified LAPTM5 as an inhibitor of clonogenicity and invasiveness of CD40-positive glioblastoma cells." (PMID 34116687, 2021). "Clinically, it was found that expression of CD40/CD40L was positively correlated with disease prognosis in glioblastoma." (PMID 34771550, 2021). "Here the authors show that IL6 blockade, in combination with a CD40 agonist, overcomes macrophage-mediated immunosuppression and sensitizes glioblastoma to immune checkpoint blockade in preclinical models." (PMID 34103524, 2021). "BAL101553 monotherapy increased survival in immune checkpoint blockade–resistant SB28 glioblastoma tumors and synergized with anti-CD40 antibody, in a T cell–independent manner." (PMID 34403371, 2021). "Especially for immune checkpoints that are less extensively studied in brain tumors, such as IDO1, TIM-3, and CD40, current knowledge is mainly based on research in other malignant brain tumors, such as glioblastoma." (PMID 34771550, 2021). "In glioblastoma, CD40-based immunotherapy showed an inhibitory effect on tumor growth in preclinical glioblastoma models in vivo." (PMID 32582531, 2020). "In conclusion, these data demonstrate that LAPTM5 mediates the sensitivity to temozolomide by the inhibition of CD40-induced NFκB pathway activation in CD40-positive glioblastoma cells." (PMID 32582531, 2020). "CTLA-4 showed stronger associations with PD-1, CD40, and ICOS in patients with glioblastoma in both databases." (PMID 31911758, 2020). "In conclusion, we identified LAPTM5 as a negative regulator of CD40-mediated NFκB signaling in glioblastoma." (PMID 32582531, 2020). "LAPTM5 relevantly inhibits the clonogenicity and the invasiveness of CD40-positive glioblastoma cells." (PMID 32582531, 2020). "This study describes the inhibiting effects of LAPTM5 on tumorigenicity in CD40-positive glioblastoma and its role as a negative regulator of CD40-mediated NFκB signaling." (PMID 32582531, 2020). "In this regard, the presented data reasonably suggest LAPTM5 expression status as a potential biomarker for sensitivity to temozolomide treatment in CD40-positive glioblastoma." (PMID 32582531, 2020). "In order to identify the underlying molecular mechanisms of LAPTM5 function, we aimed to explore the CD40–LAPTM5 interaction in glioblastoma." (PMID 32582531, 2020). "LAPTM5 expression correlated with better overall survival in glioblastoma patients depending on CD40 expression status." (PMID 32582531, 2020). "LAPTM5 was previously shown to be regulated by the CD40 receptor in immune cells and CD40 is highly expressed in up to 40% of glioblastoma." (PMID 32582531, 2020).
glioblastoma (continued). "Furthermore, LAPTM5 expression was correlated with a better overall survival in glioblastoma patients, contingent on the CD40 expression status." (PMID 39281638, 2024). "Notably, CD40 is the only biomarker that achieved a good performance in predicting ICB response in glioblastoma (AUC = 0.83)." (PMID 34758832, 2021). "Furthermore, based on the presented results, the LAPTM5 expression status provides a potential new biomarker for response to temozolomide treatment in CD40-positive glioblastoma, which merits further evaluation in clinical practice." (PMID 32582531, 2020). "In addition, as shown in vitro and in vivo, LAPTM5 sensitizes CD40-positive glioblastoma cells to temozolomide treatment, the standard chemotherapy for glioblastoma patients." (PMID 32582531, 2020). "As LAPTM5 was shown to sensitize CD40-positive U87MG glioblastoma cells to temozolomide and inhibited the NFκB pathway, the functional role of potential NFκB-mediated temozolomide resistance in LAPTM5 knockdown cells as well as the connection with CD40 expression was further investigated." (PMID 32582531, 2020). "Finally, a TCGA analysis revealed that a higher expression of LAPTM5 has a positive effect on survival in CD40-positive glioblastoma patients." (PMID 32582531, 2020). "Indeed, our data and data from other investigators suggest that the survival benefit from IL-6 plus ICI blockade is modest, but when combined with additional agents, such as CD40 stimulation or radiotherapy, this therapeutic strategy can durably prolong survival in glioblastoma preclinical models." (PMID 40161763, 2025). "Therefore, LAPTM5 may present as a potential biomarker for the sensitivity of CD40-positive glioblastoma to temozolomide." (PMID 39281638, 2024). "Thus, targeting cytokine IL-6 and stimulating CD40 to expose the glioblastoma to an immune checkpoint blockade, together may mitigate tumor antigen-mediated immune suppression while maintaining T cell infiltration in glioblastoma." (PMID 38892305, 2024). "Hence, LAPTM5 may provide a potential biomarker for sensitivity to temozolomide in CD40-positive glioblastoma." (PMID 32582531, 2020). "Based on these findings, we established a risk signature comprised of CD276, TNFRSF14, TNFSF14, TNFSF4, CD40, and TNFRSF18 to predict OS and response to immune checkpoint blockade in glioblastoma patients." (PMID 38365809, 2024). "For that, established glioblastoma cell lines were examined for membrane CD40 expression by flow cytometry, revealing only U87MG cells to be clearly positive for CD40 expression." (PMID 32582531, 2020). "In addition, we obtained representative IHC staining images of CD276, TNFSF4, TNFRSF14, CD40, TNFSF14, and TNFRSF18 in both normal tissues and glioblastoma samples from the Human Proteome Atlas." (PMID 38365809, 2024). "The co-culture of apoptotic LN-229 increased the CD40+ GFP+ cell population to ~10% in the parental, SIRPα-negative and MERTK-negative cells, showing that microglial phagocytosis was more efficient on apoptotic glioblastoma cells." (PMID 37483607, 2023). "There, genes with a higher expression in glioblastoma compared to astrocytoma were VEGFA, 4EBP1, CCL2, PLAU (uPA), CXCL8 (IL8), CXCL10 (IP10), CASP8, HGF, LIF, CD40, CDCp1, TNFRSF11B (OPG), CD274 (PD-L1), IL6, CXCL1, CCL20 (MIP3α), CCL8 (MCP2), CD244, MMP1, TNFRSF9, CXCL6, MMP10, FGF5)." (PMID 35301393, 2022). "In CD40 positive glioblastoma, LAPTM5 expression could suppress tumor growth by inhibiting CD40-mediated activation of NF-κB." (PMID 36046710, 2022). "For example, tumour-associated macrophages from glioblastoma have been reported to lack the costimulatory molecules CD86, CD80 and CD40, suggesting that they are not able to effectively support activation of T cells." (PMID 34676050, 2021). "Here, for the first time, we could demonstrate the link between CD40 and LAPTM5 in glioblastoma and characterize the role of the CD40–LAPTM5 axis in tumorigenicity." (PMID 32582531, 2020).
glioblastoma (continued). "Our results indicate that CD40 activates the NFκB pathway in glioblastoma cells only in the absence of LAPTM5 expression, leading to enhanced tumorigenicity and resistance against temozolomide." (PMID 32582531, 2020). "With the limitation imposed by the unavailability of tumor samples from time points later than nine days after treatment, we hypothesize that CD40-expressing peripheral blood DCs or monocytes may be recruited to H-1PV-infected tumors and interact with CD40L+ glioblastoma cells." (PMID 29244745, 2017). "Tumor tissue collection in this first trial, primarily designed to assess safety, did not allow performing such studies, but in future H-1PV glioblastoma trials, tumor infiltration with DCs, the CD40/CD40L axis, and costimulatory molecule expression on TAM and DCs will be worth investigating." (PMID 29244745, 2017). "Interestingly, CD40L expression in glioblastoma cells was first reported in 2015 and found to be a positive prognostic factor, while co-expression of both CD40 and CD40L in glioblastoma cells correlated with negative prognosis." (PMID 29244745, 2017).
lung carcinoma (25 papers, 2015 to 2025). "CD40 (rs1883832) polymorphism has been reported to increase susceptibility to lung cancer, Hodkin Lymphoma, and cervical cancer." (PMID 39625893, 2024). "In univariate analysis, T allele carriers (TT+CT) for CD40 rs1883832 had a higher risk for lung cancer (p = 0.002; OR 1.738, 95% CI 1.224–2.468)." (PMID 34604057, 2021). "A statistically significant difference was observed in the allele frequency of CD40 rs1883832 (T) between lung cancer patients and controls (p=0.021) as well as between the frequencies of the studied genotypes (p=0.003)." (PMID 34604057, 2021). "According to our studies as well as to other studies, CD40 expression in lung cancer patients has been associated with metastatic progression as well as with prognosis." (PMID 34604057, 2021). "Supportive to our finding is the association of CD40 expression with metastatic spread of human lung cancer cells in vitro." (PMID 31137630, 2019). "Our analysis of an orthotopic murine lung cancer model demonstrates a preferential uptake of the HNPs and anti-CD40 by the cancer cells, sparing the normal lung tissue." (PMID 40278452, 2025). "Analysis of an orthotopic murine lung cancer model demonstrated a differential uptake of the HNPs and anti-CD40 by the cancer cells." (PMID 40278452, 2025). "MAPK signalling pathways, CD40 agonists have entered clinical trials and significantly enhance the immunotherapeutic effects of lung cancer in combination with PD-1 inhibitors." (PMID 41050056, 2025). "Using an inhalation-based administration, we successfully established a treatment model of increased therapeutic efficacy with HNPs and anti-CD40 in an orthotopic murine lung cancer model." (PMID 40278452, 2025). "We successfully developed an aerosol drug delivery model to administer both anti-CD40 and HNPs in a murine lung cancer model." (PMID 40278452, 2025). "In non–small cell lung cancer (NSCLC) and breast cancer, CD40 stimulation has been associated with enhanced macrophage activation and expansion of effector T cells in murine models, contributing to tumor control." (PMID 40821795, 2025). "A previous study reported that CD40 signaling induced growth inhibition of CD40-positive lung cancer cells." (PMID 35746505, 2022). "In fact, DCs cultivated in the presence of lung cancer patient serum have shown decreased expression of CD40, CD80, CD86, MHCII, IL1 and NFκb, similarly to the results we showed here." (PMID 34535708, 2021). "Mature DCs in lung cancer express high levels of cytokines and costimulatory molecules (CD40/80/86) to activate T cells." (PMID 32206449, 2020). "In vitro, the investigators showed improved oncolysis in human CD40-positive endometrial cancer cells compared to CD40-negative lung cancer cells, as well as upregulation of markers of immunogenic cell death." (PMID 28536390, 2016). "In non–small cell lung cancer (NSCLC), CD40 agonists used as monotherapy or in combination with immune checkpoint inhibitors have led to stable disease in a subset of patients, while enhancing dendritic cell function and T cell priming." (PMID 40821795, 2025). "Various TNF family members, including CD40, OX40, 4-1BB, GITR, and CD27, which were investigated as new effective targets, are now under positive exploration for understanding lung cancer." (PMID 36505472, 2022). "DC treated with lung cancer cell culture supernatants significantly downregulated the expression of MHC class II molecules and of the costimulatory molecules CD40 and CD80, but upregulated the inhibitory molecule PD-L1/CD274." (PMID 33066260, 2020). "We show that adding Hesperetin-loaded nanoparticles to the immunoadjuvant anti-CD40 and delivery in an aerosol format is effective in treating orthotopic lung cancer in mice, even without the inclusion of radiation." (PMID 40278452, 2025).
lung carcinoma (continued). "CD40 is also expressed in breast and lung carcinomas and carcinomas of the urinary bladder, nasopharynx, and colon, in contrast to normal non-proliferating tissues, which are CD40-negative." (PMID 33747948, 2021). "To investigate the expression of E-cadherin in lung dendritic cells in the presence of different immune responses, we harvested lung tissue from the Lewis orthotopic lung cancer model, C57BL/6, Rag1 KO mice and Rag1 KO mice exposed to an anti-CD40 antibody, respectively." (PMID 25651850, 2015). "Mutations in various upstream regulators (TRAF2, TRAF3, cIAP1&2, CD40) lead to increased stability of NIK and subsequent activation of the noncanonical NF-kB pathway, and this mechanism of activation appears to be important for different cancer types including DLBC and lung cancer." (PMID 34970479, 2021).
Obesity (24 papers, 2011 to 2025). Accumulation of substantial excess body fat. "In murine obesity, coinhibitory suppression of T cell activation by CD40 protects against obesity and adipose tissue inflammation, while CD40-deficient mice display an aggravated phenotype during DIO." (PMID 35252400, 2022). "Insulin resistance has been associated with ATM MHC II antigen presentation in murine obesity and in human CD11c+ ATMs, so we examined antigen presentation–related genes HLA-D, CD40, CD80, CD86, and ICAM1 in ATM subtypes." (PMID 34990410, 2022). "Controversially, CD40 has been positively correlated with clinical parameters of obesity and associated with protection against obesity." (PMID 36297185, 2022). "The minor phenotype of the macrophage CD40 deficient mice in diet-induced obesity might be caused by the differential involvement of TRAF-adaptor molecules essential in CD40 signaling." (PMID 30096208, 2018). "Interestingly, a critical role for CD8+ in adipose tissue of diet-induced obesity on glucose tolerance and insulin resistance was also reported in relation to CD40-deficiency." (PMID 28400678, 2017). "In the hip joint, IPA analysis of the obesity‐associated DEGs revealed significant canonical pathways involved in immune signalling pathways ‘CD27 and CD40 signaling’ as well as ‘osteoarthritis’ and ‘senescence’ pathways." (PMID 37006170, 2023). "We found that CD40 expressing CD11c+ cells contribute to diet-induced-obesity (DIO) and NASH in opposing ways." (PMID 31604965, 2019). "We here investigate the contribution of CD40 on CD11c+ cells in the regulation of diet induced obesity and NASH using CD40fl/flCD11ccre mice." (PMID 31604965, 2019). "In diet induced obesity CD40 expressing CD11c+ cells play a crucial role in protection against obesity-induced ectopic lipid storage and metabolic dysfunction, most likely via induction of regulatory T cells." (PMID 31604965, 2019). "In conclusion, we here show that CD40+CD11c+ cells play a crucial role in protection against obesity-induced liver steatosis via activation of regulatory T cells, thereby inducing a tolerogenic immune response that prevents hepatosteatosis." (PMID 31604965, 2019). "During obesity, CD40 expressing CD11c+ dendritic cells (DC) and macrophages accumulate in adipose tissue and liver." (PMID 31604965, 2019). "Concerning obesity, CD40 is highly expressed in leukocytes, adipocytes and the stromal cells of adipose tissue, and is involved in the regulation of adipose tissue metabolism." (PMID 30089130, 2018). "To further explore the specific role of macrophage CD40 in adipose tissue inflammation we here subject CD40flflLysMcre and WT mice to diet-induced obesity." (PMID 30096208, 2018). "CD40 deficiency affects ATM infiltration into VAT and decreases T cell accumulation during diet-induced obesity." (PMID 30233575, 2018). "Here, we investigated the role of macrophage CD40 in diet-induced obesity using CD40flflLysMcre mice." (PMID 30096208, 2018). "Another interesting aspect to consider is the role of CD40 in obesity-related inflammation." (PMID 40519917, 2025). "Poggi and Lutgens demonstrated that CD40 engagement leads to high levels of inflammatory cytokines, which may contribute to the chronic low-grade inflammation observed in obesity." (PMID 40519917, 2025). "CD4+ and CD8+ T cells populate the human adipose tissue and the Th1:Th2 balance is highly associated with systemic inflammation and insulin resistance; in addition, MHCII and costimulators CD86 and CD40 play essential roles in obesity-induced adipose tissue inflammation." (PMID 29765984, 2018). "In conclusion, we here show that loss of macrophage CD40 signaling does not significantly affect diet-induced obesity." (PMID 30096208, 2018). "For example, recent publications on the CD154/CD40 dyad have pointed to its role in obesity and hepatic steatosis, and it is tempting to speculate that platelet CD154 contributes to metabolic homeostasis." (PMID 25763299, 2015).
Obesity (continued). "Additionally, CD40 expressing CD11c+ cells play a crucial role in protection against obesity-induced ectopic lipid storage and metabolic dysfunction, most likely via induction of Treg, however, during metabolic steatohepatitis, CD40 on CD11c+ cells contributes to liver inflammation." (PMID 33833761, 2021). "Absence of CD40 on CD11c+ cells caused increased cholesterol levels in liver and blood in obesity." (PMID 31604965, 2019). "A study showed that the adipose tissue in CD40-deficient animals has elevated cytokine levels and inflammatory cell infiltrates, particularly of macrophages and T cells, suggesting an important role of TH1 cells in regulating inflammation and insulin resistance in obesity." (PMID 29765984, 2018). "Diet-induced obesity also promotes the expression of T-cell co-stimulatory molecules, such as CD80 and CD40, on the surface of ATMs in VAT." (PMID 30233575, 2018). "In order to evaluate whether obesity affected monocytes functions we evaluated the expression of CD36, TRL-2, TRL-4 and HLA-DR, CD40, CD80/86 molecules in NW and CO." (PMID 27977792, 2016). "For example, CD40 and herpes virus entry mediator (HVEM), which are expressed on adipocytes, are considered to be mediators of contact-dependent signaling of macrophages, and ablation of these receptors reduces obesity-induced inflammatory responses." (PMID 23316108, 2012).